CDC42 (cell division cycle 42)
Diseases named in the same sentence as CDC42 in open-access papers (continued):
Sharing a sentence is not in itself a finding about the gene and the disease.
tumor (continued). "The Cdc42‐GTPase is among the most studied GTPases and is considered essential in the organisation of the cellular actin network and tumour cell motility." (PMID 30582770, 2019). "Cell division cycle 42 (CdC42) was focally positive in 5/30 cases, especially at the invasion front, and it was distributed randomly in the central tumour and invasion front in 2 cases." (PMID 29976164, 2018). "CRIB pulldown assays employing PAK-PBD in control and XIAP-depleted cells showed that the loss of XIAP also led to an increase in the GTP-bound active form of Cdc42 in normal as well as in tumor cells." (PMID 28661476, 2017). "Transcriptomic data show that Luminal A tumours are enriched for aberrant expression of genes in the cell division control 42 homolog (CDC42) pathway." (PMID 28451966, 2017). "Collectively, these data support that CDC42 functions oppositely in different lineage tumor formation: it promotes tumor growth in alveoli while prevents tumor formation in bronchioles." (PMID 28871124, 2017). "In conclusion, our studies revealed the other side of XIAP in the control of Rho GTPases (especially Rac1 and Cdc42), the prime drivers of tumor cell migration and invasion." (PMID 28661476, 2017). "Altogether, these results suggest that high levels of CDC42 are critical for tumor generation and progression in vivo in CRC." (PMID 28460460, 2017). "Depletion of XIAP led to an increased protein stability and activity of Cdc42 in normal and tumor cells." (PMID 28661476, 2017). "Here we show that XIAP contributes to Cdc42 homeostasis by direct ubiquitination leading to protein degradation thus controlling filopodia dynamics and tumor cell metastases." (PMID 28661476, 2017). "Increased Cdc42 activity positively impacts metastasis outcome by imparting resistance to anoikis and by increasing tumor invasiveness." (PMID 28371345, 2017). "In this validation cohort, survival analysis was intentionally restricted to the subgroup of patients with Dukes ́ C and D tumor, where a significant interaction between the expression of CDC42 and CACNA2D2 was found." (PMID 28460460, 2017). "In contrast, deletion of Cdc42 in alveoli cells prevents KrasG12D-induced cell proliferation, which leads to reduced tumor formation." (PMID 28871124, 2017). "The members of the Ras superfamily of small GTPases, such as Rac1, Cdc42, and RhoA, are adhesion and growth factor-activated molecular switches that play important roles in tumor development and progression." (PMID 28811522, 2017). "High nuclear CDC42 expression demonstrated a significant correlation with ER-positive, low-grade tumours and was more common in the lobular histological subtype (all p < 0.001)." (PMID 28451966, 2017). "Migration, in part regulated by RhoA, Rac1 and cdc42 small G-proteins, has a pivotal role in tumor progression and metastasis formation." (PMID 28562340, 2017). "In AECII, Cdc42 loss strongly prevents Kras-driven neoplastic transformation, establishing the tumor-promotive role of CDC42." (PMID 28871124, 2017). "CDC42 cytoplasmic staining also showed correlations with tumour size (p = 0.04) and grade (p = 0.014)." (PMID 28451966, 2017). "Cytoskeleton-regulating proteins, including rhodopsin (RHO), CDC42 and ras-related C3 botulinum toxin substrate 1 RAC1 (RAC1), which are members of the RAS family due to high similarity, are implicated in tumor metastasis." (PMID 28179017, 2017). "Depletion of XIAP also enhanced the active GTP-bound form of Cdc42 with a concomitant increase in actin-rich filopodial protrusions in normal and tumor cells." (PMID 28661476, 2017). "Our newly discovered CDC42-transcriptional signature was next tested in 628 CRC patients, where we found that the expression of 57 genes correlated with CDC42 levels in the tumor samples in the same direction as seen in SW620 cells." (PMID 28460460, 2017).
tumor (continued). "In this study, we show that PAD2 depletion or inhibition suppresses tumor cell migration, alters tumor cell morphology, and suppresses the expression of the cytoskeletal regulatory proteins: RhoA, Rac1, and Cdc42." (PMID 28549415, 2017). "Further, XIAP depletion promotes lung colonization of tumor cells in mice in a Cdc42-dependent manner." (PMID 28661476, 2017). "Our data further show that CDC42 prevents lung bronchiole tumor formation potentially through regulation of cell polarity integrity." (PMID 28871124, 2017). "PTEN is a tumor suppressor that coordinates the CDC42-PRKCZ-PARD complex and regulates spindle orientation in nonpolarized cultured cells." (PMID 27119498, 2016). "RASGRF1/2 regulates Cdc42-mediated tumor cell transformation and cell motility, working as a tumor suppressor gene." (PMID 27993161, 2016). "The tumor suppressor PTEN regulates CDC42 and apical PRKCZ activity that have a mechanistic role in spindle orientation, lumen formation and 3D epithelial morphology." (PMID 27119498, 2016). "Statistical analysis revealed that 80.4% of NSCLC specimens with high CD47 expression also exhibited strong Cdc42 staining signals, and 85.3% of the tumor samples with low CD47 expression displayed low or undetectable Cdc42 signals (X2 = 33.87, P < 0.01)." (PMID 27411490, 2016). "The identified Rac and Cdc42 selective inhibitors are effective in cell culture and recent studies demonstrate anti-tumor activity in mouse xenograft models, but these compounds have not been translated to human use." (PMID 26558612, 2015). "The Cdc42-specific GEF ARHGEF9 is up-regulated by the oncogene transcription factor CHD1L and has been previously implicated in tumor cell migration, invasion and metastasis by increasing cell motility and inducing filopodia formation." (PMID 26633832, 2015). "Fibronectin expression, activation of the FAK/Rac1/cdc42 axis downstream of fibronectin, and tumor migration were concomitantly induced by EGF." (PMID 25595899, 2015). "hsa-miR-18a, that targets CDC42 and acts as a tumor suppressor, was significantly downregulated in STIM1-enriched patients." (PMID 26543234, 2015). "Rho GTPases, members of the Ras superfamily of small GTPases such as Rac1, Cdc42, and RhoA, are adhesion and growth factor–activated molecular switches that play important roles in tumor development and progression." (PMID 26371759, 2015). "Subsequently, we found that CDC42-v1 and -v2 had different effects on filopodia formation and tumor cell behaviors." (PMID 26336992, 2015). "GDH cells retain their strategic position even in advanced GBM-xenografts and, interestingly, shed Cdc42+-particles in the lumen of dilated vessels in 7-day grafts, which are also found in sinusoidal vessels in 1-month-tumours." (PMID 25032689, 2014). "Our findings also support pre-existing evidence indicating a direct molecular interaction of Cdc42 and CD44 in association with tumor cell-actin cytoskeleton, by demonstrating that they synergize in altering vessel architecture in brain slices." (PMID 25032689, 2014). "We found that vessel co-option and flectopodia formation and function are dependent on the activity of Cdc42 in tumor cells." (PMID 25032689, 2014). "Reducing Cdc42 in tumor cells, using either siRNA (iCdc42) or the specific Cdc42-inhibitor Secramine-A, results in shortened extensions to vessels and in reduced angle of vessel bending in brain slices." (PMID 25032689, 2014). "Taken together, our data indicate that Cdc42 activity in GBM cells favors tumor-establishment over clearance." (PMID 25032689, 2014). "Rho family GTPases, including Rho, Rac, and Cdc42, have been shown to differentially and cooperatively contribute to triggering invasive behavior by tumor cells." (PMID 24908363, 2014). "Although CDC42 was predicted to be a miR-199a-3p target, CAV2 and CDC42 possessed negatively correlated expression in the studied tumour cell line MT1." (PMID 23826261, 2013).
tumor (continued). "Our experiments demonstrated that, even without optimization for in vivo utilization, pharmacological inhibition of Cdc42 with ML141 enabled TMX to suppress growth of MDA-MB 231 derived tumours." (PMID 23606532, 2013). "In striking contrast, when Cdc42 levels were decreased by shRNA expression, tumour take was reduced, with 1000 and 10,000 MDA-MB 231 cells establishing tumours in only one out of five and three out of eight NOD/SCID mice, respectively (p < 0.05)." (PMID 23606532, 2013). "When tumours were generated from Cdc42 knockdown cells, these tumours showed increased responsiveness to TMX in vivo, as compared with tumours derived from cells expressing scrambled shRNAs." (PMID 23606532, 2013). "In keeping with this latter finding, elevated Cdc42 reactivity in the tumour blood vessels was significantly correlated with the premenopausal status of patients (P = 0.026)." (PMID 23420497, 2013). "Specific GAPs can inhibit the activation of Cdc42, Rac1 and RhoA by increasing intrinsic GTPase activity, leading to suppression of tumor formation." (PMID 23538840, 2013). "When mice were transplanted with 10,000 Cdc42 knockdown cells that also expressed a secondary c-Cbl knockdown, the frequency of tumours increased from 38 to 63%, while in mice transplanted with 1000 such cells the tumour frequency increased from 20 to 60%." (PMID 23606532, 2013). "Cdc42 knockdown also inhibited generation of mammospheres in vitro and tumours in vivo, demonstrating the additional importance of this pathway in tumour initiating cell (TIC) function." (PMID 23606532, 2013). "Our findings also extend the understanding of potential contributions of Cdc42 to tumour biology in several ways." (PMID 23606532, 2013). "When examined 40 days after implantation, two out of five mice harbouring ML141 pre-treated cells started to form tumours (a comparable frequency as with Cdc42 knockdown cells)." (PMID 23606532, 2013). "The most important indicator of TIC function is the ability to generate tumours in vivo, and examination of this parameter revealed suppression of tumour initiation by Cdc42 inhibition in three different BLBC cell lines." (PMID 23606532, 2013). "Even when we transplanted 100,000 MDA-MB 231 cells with a prior Cdc42 knockdown we found that tumours grew more slowly and that animals showed longer survival." (PMID 23606532, 2013). "It is also well established that Rho, Cdc42 and particularly Rac1 have critical roles in experimental tumour metastasis." (PMID 22689141, 2012). "Perturbations in tumor progression correlated with altered integrin signaling, including decreased cell spreading, diminished p130Cas phosphorylation, and Cdc42 activation." (PMID 22569336, 2012). "Here, we report that Cdc42 is critical for oncogenic Ras-driven cell transformation and tumor growth." (PMID 22719838, 2012). "Under the control of a tetracycline regulatable promoter, dominant negative mutants of Rac1 and Cdc42 were expressed in a human HRas-transformed, tumor derived fibroblast cell line." (PMID 20067638, 2010). "Increases in activity levels of the Rho proteins Rac and Cdc42 have been shown to be accountable for the promotion of tumor cell invasiveness." (PMID 16280046, 2005). "We show that the level of RhoA, RhoB, Rac1 and Cdc42 protein is largely enhanced in all tumour samples analysed (n=15) as compared to normal tissues originating from the same individual." (PMID 12237774, 2002). "Because CDC42 signaling promotes aggressive tumor phenotypes, disruption of circRNA–miRNA–CDC42 networks may contribute to TNBC’s poor clinical outcomes." (PMID 41516402, 2026).
tumor (continued). "Increased circRNA hypermethylation may increase accumulation and sponge tumor-suppressive miRNAs, driving CDC42 activation and metastatic progression, whereas hypomethylation-linked downregulation may release miRNAs to suppress alternative oncogenic targets." (PMID 41516402, 2026). "Previous studies have found that on the one hand, Cdc42 promotes tumor transformation, tumor invasion, and metastasis; on the other hand, the knockdown of the CDC42 gene leads to dysregulated expression of key transcription factors that promote tumorigenesis or partial transformation." (PMID 40655948, 2025). "Moreover, the activation of Rac and Cdc42 by DOCK proteins not only influences tumor cell motility but also reshapes the immune microenvironment by attracting immunosuppressive cells, thereby promoting immune evasion." (PMID 41200217, 2025). "Similarly, the micropeptide pTINCR encoded by TINCR interacts with cell division control protein 42-homolog (CDC42) to enhance CDC42 SUMOylation, promoting its activation, epithelial differentiation, and tumor growth inhibition." (PMID 41181701, 2025). "Previous studies have hypothesized that: the tumor-promoting activity of the CDC42 gene is derived from CDC42-V1, while the tumor-suppressive activity is derived from CDC42-V2, but there is a lack of research on its related mechanisms." (PMID 40655948, 2025). "Analysis of 161 PDAC cases from the Clinical Proteomic Tumor Analysis Consortium (CPTAC) database revealed that NAT10 mRNA expression was positively correlated with CDC42, matrix metalloproteinase-9 (MMP9), and Paxillin (PXN), which are expressed upon the focal adhesion pathway activation." (PMID 40119353, 2025). "Our focus is on CDC42, which stimulates multiple signaling pathways promoting tumor growth." (PMID 39791593, 2025). "Moreover, miR-342-3p inhibits NPC tumor growth and invasion by directly targeting the Cdc42 pathway." (PMID 40061126, 2025). "In this study, we did not address whether combined inhibition of oxidative phosphorylation and CDC42 affects metastasis in COA4‐null tumor cells." (PMID 40936169, 2025). "This suggests that the CDC42 gene is also a tumor suppressor." (PMID 40655948, 2025). "Mutations in the CDC42 gene set could lead to the defective function of CDC42 and the inhibition of tumor growth, which further alleviates immune suppression." (PMID 39791593, 2025). "Moreover, we confirmed that tumor VCAM1 reduced CDC42 expression in human CD8 T cells as well, and that led to impaired IFN-γ production." (PMID 38332012, 2024). "In addition, genes related to tumor spreading, cell migration, and cytoskeletal reorganization were also up-regulated in vitro and in vivo, such as CDC42, DNMBP, CAPG, NRAS, BCL9L, etc.." (PMID 39063079, 2024). "Notably, knockdown of tumor Vcam1 increased CDC42 expression in both GFP+ transferred and GFP- host iNKT cells in tumors." (PMID 38332012, 2024). "Additionally, we confirmed that, in vivo, CDC42 overexpression led to enhanced tumor infiltration, IFN-γ production, and anti-tumor efficacy of iNKT cells." (PMID 38332012, 2024). "Furthermore, inhibition of Cdc42 was followed by pericytes initiating an immune response, which suppressed tumor growth in vitro and in vivo." (PMID 37686288, 2023). "This further provided important evidence for the high expression of CDC42 in most tumor tissues." (PMID 37476838, 2023). "Through online databases, we discovered that CDC42 was enriched in numerous tumor tissues." (PMID 37476838, 2023). "An alternative hypothesis is that Cdc42 activity may fluctuate throughout the process of tumour initiation, development, maintenance and subsequent migration and metastasis." (PMID 37114375, 2023). "Furthermore, the WB analysis showed that the expression levels of vimentin, PIAS1, P62, cathepsin B and D, SUMO2/3, SUMO1, and CDC42 were lower in the xenograft tumor tissues of Hct116 and LoVo control cells than in the PDCs." (PMID 37833712, 2023).
tumor (continued). "In addition, leptin is able to support the lamellipodia formation and tumor cell invasion through activation of cell division control protein 42 (Cdc42) and Ras-related C3 botulinum toxin substrate 1 (Rac1) in human tumor colorectal cell lines LS174T and HM7." (PMID 37760840, 2023). "Low acetylation level of CDC42 K153 is crucial for tumor cell migration, invasion and apoptosis." (PMID 36812247, 2023). "In fact, the feedback loop described previously, may be the reason that activated Cdc42 (G12V) has been reported to be a putative tumour suppressor in the right circumstance." (PMID 37114375, 2023). "Interestingly, when Cdc42 is inhibited in tumor cells, PCs transform into macrophage-like cells capable of phagocytizing the cancerous cells." (PMID 37174724, 2023). "Interestingly, when Cdc42 was inhibited in tumor cells, there were fewer flectopodia, less vessel bending compared to the controls, and, most importantly of all, no vessel co-option." (PMID 37174724, 2023). "Pharmacological blockade of CDC42 abrogated the compelling difference in migration and invasion ability between MDA-MB-231 cells with TTC17-knockdown shRNA or scramble control, thereby confirming that the TTC17-mediated RAP1/CDC42 pathway was responsible for tumor progression." (PMID 36895029, 2023). "CDC42 is a member of the small GTPase family and plays a role in epithelial to mesenchymal transition, angiogenesis, cell cycle progression, oncogenic transformation, migration/invasion and tumor growth." (PMID 36936942, 2023). "At last, a series of experiments proved our assumption and ML141, a CDC42 GTPase inhibitor, may be useful to prevent tumor progression for GC patients with high AFAP1L1 expression." (PMID 36631800, 2023). "Thus, the CDC42-PAK signaling axis played a crucial role in tumor formation during bacterial infection." (PMID 36812247, 2023). "Previous studies have demonstrated that emodin could inhibit RhoA and Rock1 on gene and protein levels, and it can also suppress the phosphatidylinositol 3-kinase-Cdc42/Rac1 pathway, resulting in the restrained migratory movement of tumor cells." (PMID 36969843, 2023). "Activated Rac/Cdc42 was detected in formed tumor FFPE tissues by the R-IHC-based staining." (PMID 35110666, 2022). "In addition, Rac/Cdc42 activity was higher in the invasive front of the tumor than in the central region." (PMID 35110666, 2022). "Similarly, CDC42 is a critical regulator of angiogenic sprouting and tubulogenesis in endothelial cells and promotes tumor cell proliferation and migration." (PMID 35385746, 2022). "Moreover, during extravasation, the Rho GTPases RhoA and cell division cycle 42 (Cdc42) become activated in invadopodia, which provide a motile force to guide the tumor cells through the endothelium of the capillary walls." (PMID 35869555, 2022). "Active Cdc42 can regulate intercellular adhesion, cytoskeleton formation, and cell cycle, thus affecting cell proliferation, transformation, and dynamic balance as well as migration and invasion of tumor cells by regulating the expression of effector proteins." (PMID 35154449, 2022). "In this study, we report that TINCR encodes an evolutionary conserved ubiquitin-like protein (UBL) that we have named pTINCR, which regulates epithelial differentiation by enhancing the SUMOylation and activation of CDC42, and which acts as a tumor suppressor in epithelial cancers." (PMID 36369429, 2022). "Furthermore, the potential regulatory role of Cdc42 in non-tumor diseases and malignant diseases is discussed." (PMID 35154449, 2022). "Moreover, we suggest that PRKCZ plays a tumor-promoting role in HPV+ HNSCC via Cdc42, inhibiting E-cad expression, promoting N-cad and Vim expression, and finally contributing to EMT." (PMID 36077689, 2022). "CDC42 stimulates tumor growth, angiogenesis together with metastatic potential of HCC." (PMID 36212176, 2022).